JAG1 (jagged canonical Notch ligand 1)
Diseases named in the same sentence as JAG1 in open-access papers (continued):
Sharing a sentence is not in itself a finding about the gene and the disease.
lung carcinoma (26 papers, 2013 to 2025). "In a previous study, the expression of JAG1 in lung tissues of idiopathic pulmonary fibrosis, which predisposes to lung cancer, was up-regulated." (PMID 26930648, 2016). "In a lung cancer metastasis, overexpression of the miR-200 decreased JAG1 protein levels and impeded cell growth." (PMID 36926584, 2023). "Some studies have shown that the expression of the metastasis-promoting gene JAG1 in lung cancer cells depends on activation by EGFR." (PMID 28628609, 2017). "We observed that Jag-1 was overexpressed in a fraction of human lung cancers using the GSE7670 data set and confirmed Jag-1 over-expression in human clear cell renal cell carcinomas." (PMID 28719575, 2017). "Among screened six lung cancer cell lines, we selected the most two low JAG1 mRNA level cell lines, H1299 and H838, for exogenous expressing JAG1 and the most two high JAG1 mRNA level cell lines, HOP62 and H322M, for JAG1 silencing." (PMID 26930648, 2016). "Our findings demonstrated the oncogenic role of JAG1 in lung cancer, promoting cancer invasion and metastasis." (PMID 26930648, 2016). "HSPA2, whose cellular functions in lung cancer are unclear, was higher expressed (1.4 fold in A549 cells and 1.2 fold in H226 cells) in JAG1 transfectants compared with control cells." (PMID 26930648, 2016). "In this study, we fully analyzed the NOTCH signaling in JAG1 overexpressed lung cancer cell lines by examining the proteolytic status of NICD and downstream molecules of NOTCH signaling." (PMID 26930648, 2016). "Ectopic expression of JAG1 on lung cancer cells enhanced cell migration and invasion as well as metastasis in vitro and in vivo." (PMID 26930648, 2016). "By comparison of gene transcripted RNA profiles in the cell line pair with differential invasion ability, we identified JAG1 as a potential metastasis enhancer in lung cancer." (PMID 26930648, 2016). "Given the significance of JAG1 in cancer invasion in vitro and in vivo, we further examined the impact of JAG1 on the progress of lung cancers." (PMID 26930648, 2016). "As immunotherapy has become prospering in the treatment of lung cancer and we found that JAG1 high expression may have an immunosuppressive microenvironment in this study." (PMID 36923423, 2023). "JAG1, one of the Notch ligands, was among these putative miR-153 targets and has been reported to be upregulated in lung cancer, and we evaluated its mRNA concentration in miR-153-overexpressing SPC-A-1 cells and found that it was, indeed, dramatically decreased in these cells." (PMID 32375892, 2020). "In this study, we explored the impact of JAG1 on lung cancer invasion both in vitro and in vivo." (PMID 26930648, 2016). "Although JAG1 and HSPA2 were only partially colocalized in patients’ tumor biopsy, the regulation of HSPA2 by JAG1 could be an important find for lung cancer cell malignancy." (PMID 26930648, 2016). "Therefore, JAG1 expression in lung cancers, including squamous carcinoma, may have high impact of clinical implications." (PMID 26930648, 2016). "In summary, our findings are the first to form the basis that JAG1 serves as a prognostic biomarker and JAG1/HSPA2 axis contributes to the lung cancer malignancy." (PMID 26930648, 2016). "In conclusion, this is the first study that demonstrated that JAG1 might act as a potential prognostic marker and JAG1/HSPA2 axis mediates lung cancer malignancy at least partly." (PMID 26930648, 2016). "Finally, we would like to test whether JAG1 was colocalized with HSPA2 and fluorescent immunohistochemistry staining was performed in lung cancer patients’ tissue section." (PMID 26930648, 2016). "However, whether JAG1 can be used as a prognostic biomarker in lung cancer is not well known because of insufficient evidence." (PMID 35054034, 2022).
lung carcinoma (continued). "The IGFBP2, CTGF, JAG1, and SPARC promoters are most active in the primary culture of human fibroblasts IVP-9TS, while the IGFBP2 and JAG1 promoters virtually are not active in the epithelial cells of the lung cancer Calu-1." (PMID 33804861, 2021).
colon carcinoma (24 papers, 2014 to 2025). "Chromatin immunoprecipitation experiments revealed that Kaiso associates with the DLL1 and JAG1 promoter regions in a methylation-dependent manner in colon carcinoma cell lines, suggesting that these Notch ligands are putative Kaiso target genes." (PMID 28637464, 2017). "The cause of Notch overactivation in colon cancer appears to be ligand-dependent and to correlate with elevated JAG1 expression levels." (PMID 25309874, 2014). "Depletion of APJ or Notch3 abolished APL13 or JAG1-associated proliferation of colon carcinoma." (PMID 29254197, 2017). "We performed ChIPseq using HCT116 colon carcinoma cells, identifying ~850 putative target genes associated with metabolism (e.g., Prdx5, Mdh1, Ahcy), transcription (Taf12, Tet2, histones), malignancy (Met, Blcap, Rras, Jag1, Gsk3a) and mitotic stability (Zbtb4)." (PMID 31059499, 2019). "Exogenous apelin had anti-apoptotic effects on colon cancer cells, whereas in human colon cancer cell lines, this peptide stimulated proliferation through the JAG-1/Notch3 signalling pathway." (PMID 30127323, 2018). "Recently, another demethylase KDM4C has also been shown to bind onto the JAG1 promoter to mediate β-catenin-dependent transcription of JAG1 and to maintain sphere-forming capacity in colon cancer cells." (PMID 27029061, 2016). "Apurinic-apyrimidinic endonuclease-1 (APEX1), a multiple-functional DNA repair enzyme, promotes colon cancer progression through activating the JAG1/Notch signaling pathway." (PMID 25309874, 2014). "APEX1-induced JAG1 expression in colon cancer cells, which subsequently activated Notch signaling to promote tumorigenicity, migration, invasion, angiogenesis, tumor formation, and metastasis in mouse xenograft models." (PMID 25309874, 2014). "Accordingly, deletion of the Wnt signaling inhibitor progastrin decreased JAG1 expression and Notch activation, and subsequently promoted the differentiation of colon cancer cells." (PMID 25309874, 2014). "Furthermore, deletion of JAG1 reduced tumor growth in the ApcMin/+ mouse model, confirming JAG1 as a pathological link between Wnt and Notch pathways in colon cancer." (PMID 25309874, 2014). "mRNA expression levels of NOTCH-1, NOTCH-3, NOTCH-4, JAG-1, DLL-4, Hes-1, and Hey-1 were quantified to elucidate the action of endostatin/CTX on the notch signaling pathway in colon cancer." (PMID 26762567, 2016). "In order to confirm its role on colon carcinoma, we treated LS180 cells with JAG1." (PMID 29254197, 2017). "Interestingly, apelin peptides did not increase the proliferation of the colon cancer cells, whereas it did stimulate the phosphorylation of Akt kinase, whereas in human colon cancer cell line LS180, administration of apelin-13 stimulated proliferation via the JAG-1/Notch3 signaling pathway." (PMID 29875677, 2018).
cholestasis (22 papers, 2015 to 2025). Impairment of the bile flow caused by obstruction within the liver, or outside the liver in the bile duct system. "The incidence rates of liver-related symptoms, including cholestasis and bile duct paucity, are similar in patients with JAG1- or NOTCH2-associated ALGS." (PMID 40597401, 2025). "To investigate which liver cell populations are affected by Jag1 loss of function at the onset of cholestasis, we first analyzed Jag1+/+, Jag1Ndr/+, and Jag1Ndr/Ndr livers with single-cell RNA sequencing (scRNA seq) at embryonic day (E) 16.5 and postnatal day 3 (P3)." (PMID 39358604, 2024). "The JAG1 and Notch signaling pathways play a role in bone development, and inadequate caloric intake and malabsorption of fat and fat-soluble vitamins caused by cholestasis are involved." (PMID 36447191, 2022). "The atypical fibrotic reaction, despite severe bile duct paucity and cholestasis mimics ALGS and indicates that Jag1 mutation alters the profibrotic mechanisms, which we next investigated." (PMID 39358604, 2024). "This disruption leads to severe cholestasis followed by hepatic necrosis and fibrosis within infancy, as seen in humans with AGS, which is an autosomal dominant disorder evoked by point mutations in JAG1 and less commonly NOTCH2 genes." (PMID 38731931, 2024). "Collectively, these data revealed a role for Jag1 in thymic development in a model for ALGS, apparent already at P0, preceding cholestasis." (PMID 39358604, 2024). "In response to cholestasis, CCN1 induces the activation of NF-κB through interaction with integrins αvβ3/αvβ5 to induce the expression of Jag1, which in turn activates NOTCH1 to induce cholangiocyte proliferation." (PMID 35708907, 2022).
gastric cancer (22 papers, 2011 to 2025). A primary or metastatic malignant neoplasm involving the stomach. "Hub genes containing COL5A2, JAG1, TIMP1, FGFR1, PDFGA, VEGFA, and PTK2 were collected from the gene sets and were proven to be linked to the occurrence and development of gastric cancer." (PMID 35875363, 2022). "Over‐expression of miR‐634 inhibited the proliferation, migration, and invasion of gastric cancer cell lines, and the miR‐634 target gene was JAG1." (PMID 29464926, 2018). "The expression level of JAG1 in gastric carcinoma was upregulated, which expression was inversely correlated with miR‐634 in gastric cancer." (PMID 29464926, 2018). "In order to measure the expression of JAG1 in gastric cancer, we analyzed the expression of JAG1 in 83 pairs of human gastric cancer and para cancer specimens by qRT‐PCR." (PMID 29464926, 2018). "The expression levels of JAG1 in gastric cancer cell lines and the GES‐1 cell line were measured by qRT‐PCR and western blot methods." (PMID 29464926, 2018). "Expression of miRNA‐634 and JAG1 in human gastric cancer according to patients' clinicopathological characteristics." (PMID 29464926, 2018). "The levels of JAG1 protein in gastric cancer tissues were higher than that in adjacent tissues." (PMID 29464926, 2018). "To determine the expression levels of JAG1 and miR‐124 in gastric carcinoma, we selected eight pairs of GC tissues and matched normal tissues adjacent to the tumour, and one normal gastric cell line GES‐1 and four malignant human GC cell lines (SGC‐7901, MGC‐803, BGC‐823 and KATO‐3)." (PMID 26612211, 2016). "First, the mechanism of JAG1 in gastric cancer is not clear, the role and significance of it in signaling pathway will be further studied." (PMID 29464926, 2018).
glioblastoma (22 papers, 2009 to 2026). The most malignant astrocytic tumor (WHO grade IV). "Another example of GSLCs in a hypoxic environment regulated glioblastoma chemoresistance by upregulating JAG1 and DLL4." (PMID 38324181, 2024). "miR-512 targets JAG1, which is necessary for the negative regulatory effect of exosomes on metastasis of glioblastoma." (PMID 38920983, 2024). "MiR-512-5p and Jagged1 (JAG1) expression patterns, as well as their interactions in glioblastoma, were studied." (PMID 36536420, 2022). "Mir-489-3p can also inhibit cell proliferation by targeting the brain-derived neurotrophic factor-mediated PI3K/AKT pathway in glioblastoma cells and suppress proliferation by targeting JAG1 in bladder cancer cells." (PMID 36207684, 2022). "BMSC-derived exosomal miR-512-5p inhibited glioblastoma cell proliferation and induced cell cycle arrest by suppressing JAG1 expression." (PMID 33795521, 2021). "This is further supported by another study demonstrating that mouse DLL4 or JAG1 are expressed in glioblastoma cells and reduced tumor cell proliferation in vitro, but stimulated tumor growth in vivo by modulating angiogenesis." (PMID 33430387, 2021). "We clarified the expression patterns of miR-512-5p and JAG1 along with their interactions in glioblastoma." (PMID 33795521, 2021). "miR-512-5p was downregulated in glioblastoma tissues and cells, and Jagged 1 (JAG1) was the target gene of miR-512-5p." (PMID 33795521, 2021). "Mouse DLL4 or JAG1 expressed in glioblastoma cells decreased tumour cell proliferation in vitro but promoted tumour growth in vivo." (PMID 28445154, 2017). "Furthermore, a reduction in miR-512-5p in glioblastoma played an important role in glioblastoma progression and proliferation by targeting Jagged 1 (JAG1)." (PMID 38379858, 2024). "In glioblastoma tissue and cells, miR-512-5p was downregulated, and its target gene is JAG1." (PMID 36536420, 2022). "Immunohistochemistry analyses for DLL4/JAG1 expression and microvascular formation of glioblastoma tumor tissue show enhanced expression of both Notch ligands in tumor vasculature and demonstrate a clear correlation with poor outcome in glioblastoma." (PMID 33430387, 2021). "Thus, DLL4 and JAG1 may have an inverse effect on tumor angiogenesis in glioblastoma." (PMID 33430387, 2021). "We investigated if the mutually exclusive expression of a Notch pathway ligand (JAG1) and target (HES5) consistent with lateral inhibition could be found in primary glioblastoma by examining in greater detail three previously reported, double stained GBM specimens." (PMID 25557173, 2015).
pancreatic cancer (21 papers, 2011 to 2025). "Next, we generated KrasLSL-G12D/+;Jag1flox/flox;Pdx1-Cre mice (hereafter referred to as KJC) to determine the impact of Jag1 loss on KrasG12D-induced pancreatic cancer initiation and progression." (PMID 33268505, 2021). "Moreover, analysis using two of the human data sets containing survival information found significant association between high JAG1 expression and poor overall survival among pancreatic cancer patients." (PMID 33268505, 2021). "Moreover, JAG1 has been reported to be associated with the EMT process of pancreatic cancer and resistance to anticancer drugs." (PMID 34485257, 2021). "In addition, deletion of Jag1 during organogenesis may have caused developmental defects of the pancreas, thereby setting up a precondition for Kras-induced pancreatic cancer initiation and progression." (PMID 33268505, 2021). "Notch signaling components Jag1, Maml2, and Maml3 are direct targets of miR-200 inhibition in breast and pancreatic cancer cell lines." (PMID 36076302, 2022). "Jag1 functions as a tumor suppressor in delaying pancreatic cancer precursor, while at the same time, promotes a phenotypic switch from benign cystic lesions to invasive carcinoma of the pancreas." (PMID 33268505, 2021). "Future studies using inducible CreER systems in adult mice will be required for the delineation of Jag1 functions in the pathogenesis of acinar- or ductal-originated pancreatic cancer." (PMID 33268505, 2021). "In pancreatic cancer patients, JAG1 expression is higher in cancerous tissue, and high JAG1 is associated with poor overall survival." (PMID 33268505, 2021). "However, high JAG1 expression correlates with significantly poor survival among pancreatic cancer patients." (PMID 35673567, 2022). "The ability of pancreatic cancer cells to form tumor spheres was reduced through inhibition of the Notch pathway (achieved using γ-secretase inhibitors or knockdown of Jag1/Maml2/Maml3) suggesting that cell stemness of CSCs can be induced through the Notch pathway." (PMID 36076302, 2022). "The apparent dual role of Jag1 in pancreatic cancer may be dependent on the stage of cancer initiation and progression, or the cell-of-origin of the lesion." (PMID 33268505, 2021). "Furthermore, due to its anti-apoptotic and pro-“stemness” functions, JAG1 blockade epitomizes an alluring model for combination therapy orchestrated by standard chemotherapy as demonstrated in preclinical models of ovarian and pancreatic cancer and lymphoma." (PMID 29921897, 2018). "However, cytoplasmic staining of Jag1 and nuclear staining of Notch2 were observed at the same location of consecutive sections, suggesting that Jag1 may activate Notch2 during Kras-initiated pancreatic cancer development." (PMID 33268505, 2021). "The pancreatic cancer cell line XPA3, which is known to be Notch-dependent, also showed dramatic upregulation of both JAG1 mRNA and protein in hypoxia." (PMID 25557173, 2015). "We also observed similar effects on HES1 transcript levels following co-culture of JAG1-high and -low XPA3 pancreatic cancer cells." (PMID 25557173, 2015). "Furthermore, due to its anti-apoptotic and pro-“stemness” functions, JAG1 blockade represents an attractive option also for combination therapy approaches with standard chemotherapy as demonstrated in preclinical models of ovarian and pancreatic cancer and lymphoma." (PMID 25309874, 2014). "Notch has been shown to regulate pancreatic cancer stem cells and would have a role in the acquisition of epithelial-mesenchymal transition (EMT) by inducing SNAI2 expression due to JAG1 overexpression." (PMID 22925330, 2012). "Besides, leptin is reported to induce the expression of Notch1-4, JAG1 and DLL4 in pancreatic cancer cells." (PMID 34588926, 2021).
pancreatic cancer (continued). "Overexpression of JAG1 also induced HES1, but not HEY1, in the pancreatic cancer cell line XPA3." (PMID 25557173, 2015).
liver fibrosis (20 papers, 2012 to 2025). "Our results demonstrate that Jag1 mutation concurrently impacts hepatocyte maturity and adaptive immunity, and thus modulates liver fibrosis via multiple axes." (PMID 39358604, 2024). "Aberrant Notch activity in hepatocytes has been shown to be crucial for the development of NASH-induced liver fibrosis, and increased expression of the Notch ligand Jag1 has been closely associated with Notch activation in human liver biopsies and in mouse NASH models." (PMID 36569303, 2022). "Utilising similar antibodies targeting IGF2BP3, Jag1, Notch1/3, and Hes1 as a therapeutic strategy in pre‐existing liver fibrosis models would enhance the translational value of these discoveries." (PMID 39113232, 2024). "HSC‐specific deletion of IGF2BP3 enhanced HSC FPT and impeded their activation, thereby reducing liver fibrosis through the IGF2BP3/Notch/Jag1 signalling pathway." (PMID 39113232, 2024). "This study linked IGF2BP3 depletion to Notch‐Jag1 signalling in HSC activation and liver fibrosis development." (PMID 39113232, 2024). "Similar with the previous studies, Jag1 expression was enhanced during liver fibrosis, which was obviously down-regulated by kaempferol." (PMID 35721153, 2022). "miR-26b-5p was shown to be decreased in CCl4 mice and primary HSC, whereas enhanced Jag1 was found in liver fibrosis." (PMID 35721153, 2022). "Activation of the Jag1 gene expression by hepatocytes can enhance liver fibrosis, including through the activation of hepatic stellate cells." (PMID 36355906, 2022). "In order to investigate the striking early onset of hepatic fibrosis at 4 weeks of age in the Jag1 conditional/null mutant animals, we performed PCR array analysis specifically for genes related to the extracellular matrix (ECM Array, SA Biosciences)." (PMID 24391948, 2013). "Furthermore, targeting the IGF2BP3/Notch/Jag1 signalling axis presents a promising therapeutic approach for treating liver fibrosis." (PMID 39113232, 2024). "In mice, treatment with Jag1-ASO alleviates NASH diet-induced liver fibrosis." (PMID 36569303, 2022). "We also provide a new insight of the critical roles of miR-26b-5p-mediated Jag1 in liver fibrosis." (PMID 35721153, 2022). "Furthermore, Notch ligands (Dll1, Dll4, Jag1) and downstream molecule (Hes1) were also significantly induced in fibrotic mice versus olive-oil treated non-fibrotic control livers signifying the role of Notch pathway in liver fibrosis." (PMID 26658360, 2015).